CA9 (carbonic anhydrase 9)
Diseases named in the same sentence as CA9 in open-access papers (continued):
Sharing a sentence is not in itself a finding about the gene and the disease.
renal carcinoma (56 papers, 2003 to 2026). A carcinoma arising from the epithelium of the renal parenchyma or the renal pelvis. "CA9 has previously been found to be associated with poor prognosis in other cancers (breast, lung, cervical, and renal cancer) and in gliomas, supporting these results." (PMID 38473425, 2024). "Overexpression of CA9 correlates with tumour progression, metastasis, and poor prognosis in cancers including renal carcinomas, cervical squamous carcinomas, oesophageal carcinomas, bladder carcinomas and non-small cell lung carcinomas." (PMID 40871563, 2025). "We then confirmed that both breast and renal carcinoma cells express CA9 and different subunits of the proton pump V-ATPase and that CA9 expression was augmented when cells were exposed to hypoxic conditions." (PMID 34124067, 2021). "In our earlier studies, antibodies against CK20, EpCAM and CA19–9 were used to detect metastatic colon cancer cells and antibodies against CK18, CA9, and Cadherin 6 were used to detect renal cancer cells in lymph nodes." (PMID 30290760, 2018). "The NanoVelcro platform combined with CA9-/CD147-capture antibodies demonstrated significantly higher efficiency for capturing both CTC-mimicking renal cancer cells and RCC CTCs in peripheral blood, compared to the conventional EpCAM-based method." (PMID 27494883, 2016). "Co‐staining for carbonic anhydrase 9 (CAIX), to detect renal cancer cells, and CK7, to detect pneumocytes, demonstrated the infiltration of cancer cells into the normal alveolar walls at the tumour–lung interface." (PMID 27859259, 2017). "To examine the renal CTC-capture efficiency of using CA9 and CD147 as capture antigens, we first used the NanoVelcro platform to capture renal cancer cells from two representative human CCRCC lines, Caki-1 and Caki-2." (PMID 27494883, 2016). "An early study showed that both CA9 and CA12 expression could be suppressed in renal carcinoma cell lines by expression of the wild-type VHL gene." (PMID 35582034, 2021). "Furthermore, besides cervical epithelium, CA9 exhibits a unique feature of being expressed in several types of tumors, such as renal carcinoma, but in contrast to the pattern of CK19 expression, CA9 is not expressed in the corresponding normal tissues of these types of cancer." (PMID 24527437, 2014).
glioma (54 papers, 2007 to 2026). A benign or malignant brain and spinal cord tumor that arises from glial cells (astrocytes, oligodendrocytes, ependymal cells). "Gene Ontology (GO) analysis identifies CA9 as a potential diagnostic biomarker for AD, while knockdown of CA9 has been shown to mitigate lipid peroxidation in glioma cells." (PMID 41465406, 2025). "In line with this, knocking down or inhibiting CA9 has been shown to increase the susceptibility of glioma cells to temozolomide." (PMID 38473425, 2024). "The high-risk group displayed elevated expression levels of CA9, IL-2, and IL-6 in the glioma tissues." (PMID 39574472, 2024). "To validate the findings obtained from the bioinformatic analysis, we conducted IHC assays for CA9 (a biomarker of hypoxia and glycolysis), IL-2, and IL-6 proteins in glioma tissues obtained from our research cohort." (PMID 39574472, 2024). "In this context, knockdown of CA9 expression by glioma cells in hypoxia, an environment known to increase radioresistance of glioma cells, altered the expression of proteins involved in iron regulation and enhanced ferroptosis induced by radiation." (PMID 38099193, 2023). "We next evaluated CA9 expression in the TCGA glioma database and identified higher expression of CA9 in GBM (grade IV glioma) compared to low-grade glioma." (PMID 35874663, 2022). "In several glioma cell models, CA9 strongly co-localized with HIF-1α, indicating its induction in hypoxic regions of this tumor type." (PMID 31414377, 2019). "HIF1α activates target gene expression involved in vascularization, glucose transport, energy metabolism, and growth and metastasis, including VEGF, PDK1, Cyclin-D2, and CA9, and makes glioma cells adapt to hypoxic environments." (PMID 30082910, 2019). "As a control, in the U87 glioma cells we also measured the overexpression of the CA9 (carbonic anhydrase IX), HIG2 (hypoxia-inducible gene-2) and LOX (lysyl oxidase) genes that have been reported to be overexpressed by hypoxia." (PMID 21655185, 2011). "Additionally, the CA9 protein was also chosen for validation due to its previously reported functions in glioma treatment resistance and prognosis." (PMID 38473425, 2024). "Notably, within the subset of IDH wt gliomas in the CGGA and TCGA databases, higher levels of HIF1α and CA9 expression were linked to worse patient survival." (PMID 39346536, 2024). "In addition, CA9, a protein previously reported to be involved in resistance and prognosis in glioma, was also validated in this cohort." (PMID 38473425, 2024). "Three proteins, CA9, CYFIP2, and LGALS3BP, were found to be associated with glioma progression and, in univariate analysis, could be used as prognostic markers." (PMID 38473425, 2024). "We detected genes upregulated in PBT030 cells, such as SOX2, MYCN, NOS2, RUNX2, and VEGFA, while PBT147 cells upregulated level of PTEN, STAT6, CA9 and TLR2, demonstrating differences among PBT cell lines, which can be explained by various driving mutations and heterogeneity in glioma lines." (PMID 38449858, 2024). "Gliomas predominantly express carbonic anhydrase 9 (CAIX) and aquaporins 1 and 4 (AQP1 and AQP4)." (PMID 24198789, 2013). "In comparison to other glioma subtypes, the GS2 exhibited higher expression levels of IBSP, PLA2G2A, NNMT, CA9, and MMP9, while the GS5 showed higher expression levels of CHI3L1, IGFBP2, EMILIN3, MEOX2, and PDPN." (PMID 38332637, 2024). "Hypoxic wt-IDH glioma tissues from patients show a glycolytic phenotype due to the upregulation of PGK1, PKM2, LDHA, SLC16A3, and CA9 via HIF1." (PMID 38786726, 2024). "MCT1 and NHE1 expression is higher at the leading edge of tumors in GBM patients and in a rat glioma model; in contrast, MCT4 is upregulated in the perinecrotic tumor center, along with HIF1α, LDH, and CA9." (PMID 38786726, 2024).
glioma (continued). "Consequently, intercellular interactions between MES‐like malignant cells and M2‐like TAMs may contribute more to the recurrence of IDH wild‐type gliomas, which may further result in a more serious tumor‐suppressive effect of immune cells due to the increase of CA9 in the IDH wild‐type gliomas." (PMID 37194413, 2023). "Immunohistochemical staining revealed that five genes (ZEB1, CA9, HSPb1, STAT3, and TNFAIP3) had a higher expression in glioma tissues than in normal tissues." (PMID 35711838, 2022). "Together as a panel, CA9, CYFIP2, and LGALS3BP were able to be used as a multi-gene prognostic index, highlighting the utility of these three molecules for predicting prognoses of glioma patients." (PMID 38473425, 2024). "Moreover, ZEB1, CA9, HSPB1, STAT3 and TNFAIP3 of the overlapping genes were upregulated in glioma tissues." (PMID 35711838, 2022). "CA9 expression was investigated as a potential indicator of the efficacy of HIF-1 inhibition and the resulting radiosensitivity of malignant glioma cell lines was determined by clonogenic assay after irradiation under normoxic (2-10 Gy) or hypoxic (2-15 Gy) conditions." (PMID 21050481, 2010). "Indeed, we observed significant negative correlations between ClockLoss and HIF-1A targets (CA9, VEGFA and LDHA) in glioma." (PMID 31014368, 2019).
melanoma (48 papers, 2008 to 2026). A malignant, usually aggressive tumor composed of atypical, neoplastic melanocytes. "Patients with higher proportions of CD3+ T-cells and CD3+CA9+ T-cells within the 20 μm distance to GLUT1+ melanoma cells had significantly longer progression-free survival (p = 0.0133 and p = 0.0378, respectively)." (PMID 41559679, 2026). "To verify that the lentiviral construct expressing CA9 was functional, we first transduced WM3629 human melanoma cells with the CA9-encoding lentivirus." (PMID 36380966, 2022). "The expression levels of CA9 and EGLN2 are significantly upregulated under hypoxic conditions in the malignant melanoma cell line A375." (PMID 40001606, 2025). "Immunohistochemically, tumor cells were positive for cytokeratin and vimentin, but negative for cytokeratin 7 (CK 7), thyroid transcription factor-1 (TTF-1), carbonic anhydrase-9 (CA-9), paired box gene 8 (PAX8), leukocyte common antigen (LCA), and human melanoma black 45 (HMB45)." (PMID 33950950, 2021). "Analysis of tumor tissue revealed an increase of CA9 protein levels in mVASH1 overexpressing melanoma, whereas VEGF protein levels were not significantly altered." (PMID 19682397, 2009).
bladder cancer (40 papers, 2002 to 2025). "CA9 can not only be used as a prognostic marker for bladder cancer, previous studies have shown that high CA9 expression is associated with poor prognosis of TSCC." (PMID 34878732, 2022). "CA9 is overexpressed in urinary bladder cancer and is a potentially promising diagnostic marker for the disease." (PMID 35586208, 2022). "The overexpression of MMP10 was associated with higher grade disease, while overexpression of MMP10, PAI1, SDC1 and ANG were associated with high stage bladder cancer and CA9 was associated with low stage bladder cancer." (PMID 31905599, 2019). "One published report suggests a tripartite role of CA9 as a diagnostic, prognostic, and therapeutic molecular marker in bladder cancer." (PMID 24349364, 2013). "It suppresses cell proliferation and the transition from the G0/G1 phase to the S phase in bladder cancer by suppressing the expression of carbonic anhydrase IX (CA9), thereby diminishing tumor formation." (PMID 38915462, 2024). "A close correlation between [18F]FDG PET/CT accumulation in cancer tissue and CA9 expression has been reported, and a correlation between CA9 expression and lymph-node metastasis in breast and bladder cancer was described." (PMID 39471162, 2024). "Carbonic anhydrase (CA-9) is overexpressed in bladder cancer and is considered a molecular biomarker of this disease." (PMID 37371709, 2023). "Univariate analysis indicated age, race, MMP9, IL8, VEGFA, CA9, PAI1, ApoE, A1AT, ANG and MMP10 were associated with bladder cancer." (PMID 33823873, 2021). "It was found that ISO down-regulated the expression of PPARγ, PTEN, AKT, and CA9 proteins in the PPARγ/PTEN/AKT signaling pathway in bladder cancer cells, inhibited the activity of proliferation-related proteins, and thus, inhibited the occurrence and progression of bladder cancer." (PMID 40507124, 2025). "Furthermore, it was reported that high expression of CA9 was more frequent with advanced stage in several kinds of solid tumors including bladder cancer." (PMID 24349364, 2013). "Consistently, it has been found that hypoxia-related genes CA9, NDRG1, SLC2A1, P4HA1 and ENO1 induced EMT in hepatocellular carcinoma, bladder cancer, laryngeal cancer and gastric cancer, respectively." (PMID 34136390, 2021). "Because pathways of both pH regulation (CA9) and angiogenesis (VEGF) are regulated by hypoxia, we have compared the expression patterns of CA IX and VEGF in superficial and invasive bladder cancers." (PMID 11953885, 2002). "Moreover, downregulation of CA9, NDRG1, SLC2A1, VEGFA, and upregulation of MDM2 were further verified in an additional bladder cancer cell line, 5637 cells." (PMID 38339062, 2024). "The expression of seven of the 10 bladder cancer -associated diagnostic signature (MMP9, MMP10, PAI1, CA9, APOE, SDC1, and ANG) showed a positive association with bladder cancer diagnosis, while IL8 and A1AT showed a negative correlation with cancer diagnosis." (PMID 31905599, 2019). "CA9, which is not expressed in most benign tissues, is abundant in many cancers including renal cancer, bladder cancer, oral cancer, lung cancer and uterine cancer and has been thought to be an endogenous marker for tumor hypoxia." (PMID 24349364, 2013). "CA9 expression is suggested to be a strong predictor of recurrence, progression, and overall survival of bladder cancer patients because it was expressed differentially in noninvasive versus invasive tumors, in low-grade versus high-grade bladder cancer, and in primary tumors versus metastases." (PMID 24349364, 2013). "Previously, we showed that necrosis, HIF-1α and CA9 but not Glut-1 or a 26-gene head and neck signature predicted benefit from the addition of CON to RT in patients with bladder cancer." (PMID 27441495, 2016).
bladder cancer (continued). "Under our experimental conditions, HIF-1α-target gene CA9 but not HIF-1α-unrelated RPL13A was induced in T24 cells following CDDP exposure, indicating that CDDP enhances the expression and the transcriptional activity of HIF-1α in bladder cancer cells." (PMID 32522234, 2020).
breast tumors (40 papers, 2003 to 2025). "In another study in the literature, the authors reported that the CA9 gene was detectable in breast tumors and was associated with resistance to both adjuvant chemotherapy and endocrine therapy." (PMID 37958210, 2023). "In conclusion, we describe here that CA9 is detectable in breast tumours and is associated with resistance to both adjuvant chemotherapy and endocrine therapy." (PMID 12865916, 2003). "Since 30 of the 102 breast tumors showed a pathological complete response, these cases were excluded from the evaluation of CA9 expression." (PMID 24893880, 2014). "Moreover, the study found that PADI2 can regulate ACSL4, BINC3 and CA9 expression to advance abnormal lipid metabolism and cell invasion in breast tumors." (PMID 27478411, 2016). "CA9 has been shown to maintain the survival of breast tumor cells under hypoxic conditions." (PMID 24893880, 2014). "The CA9 expression of primary breast tumors before NAC was analyzed using CNB specimens." (PMID 24893880, 2014). "CA9 expression of breast tumors was analyzed using both CNB specimens and resected tissues." (PMID 24893880, 2014). "PADI2 affects tumorigenesis in breast tumor cells by regulating the expression of ACSL4, BINC3 and CA9, which are known to promote abnormal lipid metabolism and cell invasion of tumors." (PMID 27478411, 2016). "IF staining in matched pairs of HR-deleted breast tumors and matched normal tissue revealed an increase in H3K9 methylation in the tumor, coupled with increased expression of CDK15 and CA9 but decreased expression of CELF2, consistent with the qRT-PCR and RNA-seq results." (PMID 36230572, 2022). "Moreover, a simultaneous increase in the expression of CA9 and EGLN3 was observed in the study for the functional relationship between gene transcriptional activity and the response to lactic acidosis and hypoxia in breast tumor cells." (PMID 34046336, 2021). "These biological effects may contribute to lack of response to traditional therapy by breast tumors expressing high levels of CA9." (PMID 33330580, 2020).
colon carcinoma (40 papers, 2009 to 2025). "Yet, the influence of CA9 gene variants on the susceptibility to colon cancer remains mostly unexplored." (PMID 35812185, 2022). "This study unveiled a potential role of CA9 gene polymorphisms in many aspects of colon cancer progression." (PMID 35812185, 2022). "Consistent with this possibility, decreasing pHi by genetic silencing of NHE1 or carbonic anhydrase 9 significantly reduces the growth of colon cancer cells." (PMID 37353491, 2023). "In these two pairs of colon cancer cell lines (Hct116 and Lovo), we found CA9 mRNA decreased in both Hct116 and Lovo OLA1-KO cell lines." (PMID 35440019, 2022). "Our CA9-ko cells confirm previous reports for the important role of CA9 in promoting colon tumor cell proliferation." (PMID 28055960, 2017). "In summary, we have provided cellular knockout models to demonstrate that both NHE1 and CA9 act as important proteins for colon tumor cell progression." (PMID 28055960, 2017). "The capacity for colon tumor cells to induce compensatory CA isoforms in the face of CA9 and/or NHE1 disruption will require consideration in future inhibitor development." (PMID 28055960, 2017). "The expression of CA9 in the FFPE colon cancer specimens was then examined by IHC using the anti-CA9 antibody." (PMID 26009875, 2015). "This conclusion is supported by our IHC staining in colon cancer tissues based on a well-characterized hypoxia surrogate marker, CA9." (PMID 26009875, 2015). "This conclusion is supported by a positive correlation between CEMIP expression and the hypoxia marker CA9 in human colon cancer cells as well as several lines of in vitro biochemical and biological studies." (PMID 26009875, 2015). "Upregulated CA9 has been found at the invasive front of gastric cancers that is in agreement with our observation in human colon cancer." (PMID 26009875, 2015). "In our study, the lower expression of CA9 in left colon cancer suggests that it may respond better to treatment in this regard." (PMID 41441010, 2025). "In accordance with our data, simultaneous knockdown of CA 9 and CA 12 in colon carcinoma cells resulted in stronger radiosensitization than single knockdown of either CA 9 or CA 12, which is possibly due to a rescue mechanism between CA IX and CA XII." (PMID 34445506, 2021). "Indeed, a positive correlation of HIF-2α expression with CA9 was observed in human colon cancer SW-480 cells cultured under hypoxic conditions." (PMID 26009875, 2015). "Interestingly, cell surface staining of CA9 in colon cancer cells positively correlates with cytoplasmic staining of CEMIP." (PMID 26009875, 2015). "Normal mucosa adjacent to colon tumors and most of the colon cancer cells near the mucosal surface were negatively stained for CA9, whereas cancer cells located at the invasive front within deep mucosa or invading into the submucosa showed strong cell surface staining for CA9." (PMID 26009875, 2015). "Similarly, the majority of colon cancers show strong membranous expression of the HIF-1 target gene CA9 (67%, 110/165), consistent with other series." (PMID 19844231, 2009). "Moreover, this genetic association was detected exclusively in colon cancer but not in rectal cancer, indicating an anatomical site-specific effect of CA9 gene polymorphisms on the progression of colorectal malignancies." (PMID 35812185, 2022). "Furthermore, it is intriguing that rs2071676 was exclusively associated with clinical variables of colon cancer but not with that of rectal cancer, revealing an anatomical site-specific effect of CA9 gene polymorphisms on the progression of colorectal malignancies." (PMID 35812185, 2022). "The positive correlation between CD68 and HIF1A, and the increased CA9 and LOX expression in CD68HighHIF1AHigh patients were validated on the Oncomine database (colon cancer Bittner cohort, with the highest number of patients)." (PMID 32231135, 2020).